DPP4 (dipeptidyl peptidase 4)
Diseases named in the same sentence as DPP4 in open-access papers (continued):
Sharing a sentence is not in itself a finding about the gene and the disease.
type 2 diabetes (continued). "However, other studies suggest that patients with type 2 diabetes starting treatment with SGLT2 inhibitors experience a higher incidence and mortality of sepsis compared to those treated with DPP4 inhibitors." (PMID 40124361, 2025). "This study aimed to provide real‐world evidence on the comparative cardiovascular safety of low‐affinity cardiac mitoKATP channel sulfonylureas and DPP‐4 inhibitors, as well as high‐affinity sulfonylureas versus DPP‐4 inhibitors, in a nationwide population of patients with type 2 diabetes." (PMID 41017568, 2025). "DPP-4 inhibitory peptides, such as the PPPPPY screened in this study, may exhibit weight-neutral properties, making them suitable for obese patients with type 2 diabetes." (PMID 40509444, 2025). "effect: 0.23; CI, 0.02–0.44; p=0.03 for FinnGen), which implies the mediation analysis support that DPP4 gene expression at the mRNA level has a direct effect on HF, which is not mediated by type-2 diabetes for both two data sources." (PMID 40904650, 2025). "The patient had type 2 diabetes managed with long-term insulin and no history of DPP-4 inhibitor use." (PMID 41019039, 2025). "Dipeptidyl peptidase-4 (DPP-4) inhibitors including the DPP-4 inhibitor class of glyptins (e.g., sitagliptin, vildagliptin, linagliptin), are treatments approved for the treatment of type 2 diabetes." (PMID 39422941, 2024). "Thus, inhibiting DPP4 activity is an effective strategy for reducing blood glucose levels by preventing the breakdown of plasma GLP-1 for the treatment of type 2 diabetes mellitus (T2DM)." (PMID 38707340, 2024). "DPP4 inhibitors and GLP-1 receptor agonists, i.e., derivatives rendered less sensitive to cleavage by DPP4, have thus become two important classes of drugs for the management of type II diabetes and obesity." (PMID 39468329, 2024). "One such incretin agonist is a dipeptidyl peptidase 4 (DPP-4) inhibitor, such as saxagliptin, first approved by the US Food and Drug Administration, and now widely used in over 66 countries including China as an oral hypoglycaemia agent for type 2 diabetes." (PMID 37076476, 2023). "The role of DPP4 in metabolic and age-related diseases originated with the discovery that this exopeptidase selectively cleaves N-terminal dipeptides, inactivating GLP-1 and thereby restoring glucose homeostasis and improving type 2 diabetes." (PMID 37097759, 2023). "DPP-4 inhibitors are widely used and tolerated in the management of type 2 diabetes mellitus (T2DM) with minimal or no hypoglycemia as an adverse effect." (PMID 36180664, 2022). "Dipeptidyl peptidase 4 inhibitors, glucagon-like peptide 1 receptor (GLP-1R) agonists, and sodium-glucose cotransporter-2 (SGLT2) inhibitors have been rigorously evaluated through cardiovascular outcomes trials in the management of type 2 diabetes." (PMID 36561085, 2022). "The study concluded that significant effect of Dipeptidyl peptidase-4 inhibitor on reduction of hospitalization, lipid profile and also ASCVD risk score of type-II diabetes mellitus patients regardless of clinical comorbidities." (PMID 35763504, 2022). "Dipeptidyl peptidase-4 (DPP-4) inhibitors which increases GLP-1 and gastric inhibitory polypeptide (GIP) incretin hormone concentrations and GLP-1 receptor (GLP-1R) agonists are now widely used to treat type 2 diabetes and obesity." (PMID 36296337, 2022). "In contrast to GLP-1RAs, dipeptidyl peptidase-4 (DPP-4) inhibitors have minimal, if any, effect on gastric emptying in type 2 diabetes, although their postprandial glucose lowering may be greater in individuals in whom gastric emptying is relatively faster." (PMID 36194250, 2022). "The study also concluded significant effect of Dipeptidyl peptidase-4 inhibitor on reduction of hospitalization, lipid profile and also ASCVD risk score of type-II diabetes mellitus patients regardless of clinical comorbidities." (PMID 35763504, 2022).
type 2 diabetes (continued). "Alternatively, the combination of WP 631 and sitagliptin (a dipeptidyl peptidase-4 inhibitor used for the treatment of type 2 diabetes) did not enhance the cytotoxic effects of WP 631 on HepG2 cells." (PMID 35186762, 2022). "The enzyme dipeptidyl peptidase 4 (DPP4) can rapidly degrade glucagon-like peptide 1 (GLP-1), which increases insulin secretion and improves insulin sensitivity, making it a promising therapeutic target for type 2 diabetes." (PMID 36477638, 2022). "DPP-4 is also expressed in subcutaneous and visceral adipose tissues and it has been recently shown that the level of circulating soluble form of DPP-4, identified as adipokine, is increased in obesity and type 2 diabetes." (PMID 34930319, 2021). "Drugs used to treat type 2 diabetes such as Metformin, were reported to modify the gut microbiome, whereas information about DPP4 and SGLT2 inhibitors is lacking." (PMID 33613481, 2021). "We conclude that outpatient use of a DPP-4 inhibitor does not affect the clinical outcomes of patients with type 2 diabetes who are hospitalized because of COVID-19 infection." (PMID 34222054, 2021). "A recent study also demonstrated the effectiveness of DPP4 inhibitor sitagliptin in treating COVID-19 patients with type-2 diabetes although its mechanism of action in COVID-19 patients is not clear." (PMID 33430081, 2021). "The potential role of DPP4 inhibitors in COVID-19- infected patients with type 2 diabetes is not completely clarified." (PMID 34068970, 2021). "Moreover, DPP4 is an adipokine with increased expression in obesity, FL, and type 2 diabetes mellitus (T2DM), abnormalities that coexist with chronic inflammation." (PMID 34178021, 2021). "We examined whether weekly DPP4 inhibitor omarigliptin (OMG) can improve liver function as well as levels of inflammation and insulin resistance in type 2 diabetic patients with non-alcoholic fatty liver disease (NAFLD)." (PMID 33691757, 2021). "As GLP-1 is rapidly degraded by dipeptidyl peptidase-4 (DPP-4), DPP-4 inhibitors that are widely used to treat type 2 diabetes could be a potential treatment for DKD in part because of their pleiotropic actions." (PMID 32238837, 2020). "As inhibition of DPP-4 prolongs the life of incretins (GLP-1 and GIP), which in turn induce insulin secretion, many DPP-4 inhibitors like sitagliptin and vildagliptin are emerging as powerful adjuncts in the treatment of type 2 diabetes." (PMID 32282828, 2020). "Sitagliptin, a highly selective DPP‐4 inhibitor, as an available anti‐diabetic agent, is generally used in clinical treatment of type 2 diabetes, without common adverse effects, relevant drug interactions and cardiovascular risk." (PMID 32573108, 2020). "Actually, in the clinical trial, DPP-4 inhibitor lowered the albuminuria in type 2 diabetic patients, and this was independent of the level of HbA1C." (PMID 33267804, 2020). "Previous studies investigating DPP-4 inhibitor therapy mainly sitagliptin and vildagliptin, in a type 2 diabetes population found that there was no significant reduction in HbA1c values with treatment." (PMID 32493344, 2020). "On the other hand, the results of placebo-controlled non-inferiority randomized clinical trials suggested that DPP-4 inhibitors have a neutral effect of cardiovascular events in patients with type 2 diabetes." (PMID 31910850, 2020). "Dipeptidyl peptidase (DPP)-4 inhibitor is used for the treatment of type 2 diabetes without body weight gain." (PMID 30992469, 2019). "Indeed, serum EPA levels are related to the effect of dipeptidyl-peptidase IV (DPP-4) inhibitor, which decreases blood glucose levels through increasing circulating GLP-1 levels, in Japanese patients with type 2 diabetes." (PMID 30704490, 2019). "Among 772 121 patients with type 2 diabetes in the MDV database in the study period, a total of 5247 satisfied the eligibility criteria, of which 990 were treated with an SGLT2 inhibitor and 4257 were treated with a DPP‐4 inhibitor." (PMID 31050099, 2019).
type 2 diabetes (continued). "Besides GLP-1, DPP-4 also has other substrates and their elevation by DPP-4 inhibition can also contribute to a normalization of glycaemia in type 2 diabetes (“indirect target” or “off-target”)." (PMID 31275246, 2019). "However, this was the first study to evaluate the effects of DPP-4 inhibitor, statin, and n-3 PUFA combination therapy on lipoprotein particle and glycemic control in patients with type 2 diabetes and hypertriglyceridemia." (PMID 29544483, 2018). "Incretin-related drugs, such as dipeptidyl peptidase-4 (DPP-4) inhibitors and glucagon-like peptide-1 (GLP-1) receptor agonists, lower blood glucose in patients with type 2 diabetes through a transient glucose-dependent stimulation of insulin and suppression of glucagon secretion." (PMID 30285859, 2018). "Levels of both membrane-bound DPP-4 protein and plasma DPP-4 enzymatic activity are altered in several pathophysiological states, including cancer, inflammation, infections, immune disorders, type 2 diabetes, and kidney disease." (PMID 29491123, 2018). "Hence, we investigated the effect on plasma concentrations of LDL-C subspecies in type 2 diabetic patients treated with the SGLT-2 inhibitor, dapagliflozin, compared with patients treated with the dipeptidyl peptidase-4 (DPP-4) inhibitor, sitagliptin." (PMID 28086872, 2017). "We enrolled 212 participants with type 2 diabetes to whom DPP-4 inhibitor was administered for over 1 year without an addition or increase of other hypoglycemic agents." (PMID 28626771, 2017). "The target intervention was DPP-4 inhibitors compared to placebo, no treatment, other drugs to treat type 2 diabetes or a non-pharmacological intervention." (PMID 29047372, 2017). "In conclusion, a DPP-4 inhibitor and an SGLT2 inhibitor, when added to metformin and/or a sulfonylurea, have a modest beneficial effect in glucose control and have different effects in lipid profile in patients with type 2 diabetes." (PMID 28403877, 2017). "Furthermore, we applied this approach to analyze ADEs of incretin-based drugs such as DPP-4 inhibitors and GLP-1 receptor agonists, which are widely used to treat type 2 diabetes." (PMID 26989609, 2016). "Therefore, GLP-1 has been extensively studied as a possible treatment of type 2 diabetes, and GLP-1 analogues and DPP-4 inhibitors are now widely in clinical use in these patients." (PMID 27110066, 2016). "Therefore, GLP-1-based therapies such as GLP-1 receptor agonists and inhibitors of dipeptidyl peptidase-4, which is a GLP-1 inactivating enzyme, have been developed for treatment of type 2 diabetes." (PMID 27110066, 2016). "Since plasma DPP-4 activity is increased in patients with NAFLD and patients who have type 2 diabetes with elevated liver enzymes, treatment with DPP-4 inhibitors may prevent the development of NASH." (PMID 27462372, 2016). "The effects of DPP-4 inhibitors on bone fractures in type 2 diabetes patients have not been well documented." (PMID 27384445, 2016). "Dipeptidyl peptidase IV (DPP-4) enzyme is responsible for the degradation of incretins that stimulates insulin secretion and hence inhibition of DPP-4 becomes an established approach for the treatment of type 2 diabetics." (PMID 27832184, 2016). "Moreover, we have found that DPP-4 inhibitor alogliptin treatment blocks the AGEs-RAGE axis and resultantly reduces albuminuria in type 2 diabetes patients." (PMID 25582643, 2015). "Drugs focusing on the incretin system, such as dipeptidyl peptidase 4 inhibitors (DPP-4i) and glucagon–like peptide −1 (GLP-1) analogues have been recently introduced in the clinical practice for the treatment of diabetes type 2 demonstrating efficacy and a favorable safety profile." (PMID 26355765, 2015). "However, various anti-diabetic drugs, such as metformin, dipeptidyl peptidase 4 (DPP4) inhibitors, although it has been successfully work to blood glucose lowering in type 2 diabetes, have been repurposed from other clinical indications to treat renal injury." (PMID 25495844, 2014).
type 2 diabetes (continued). "Some studies showed anti-inflammatory effects of selective DPP-4 inhibitors in patients with type 2 diabetes, while others failed to prove the effects." (PMID 25140306, 2014). "As studies have shown that the gut incretin content is altered in animal models of type 2 diabetes, therefore AEATP may act by increasing incretin, that is, increasing glucagon-like-peptide-1 (GLP-1) or inhibiting dipeptidyl peptidase-4 (DPP-4)." (PMID 25121104, 2014). "Well-controlled type 2 diabetes patients have intact GLP-1 response to glutamine ingestion and glutamine (30 g) or glutamine (15 g) in combination with the DPP-4 inhibitor sitagliptin (100 mg) decreases postprandial glycaemia and increases circulating insulin and GLP-1 when administered with a meal." (PMID 25412338, 2014). "Moreover, we have very recently found that DPP-4 inhibitor alogliptin treatment blocks the AGE-RAGE axis and resultantly reduces albuminuria in type 2 diabetes patients." (PMID 23984879, 2013). "Recently, DPP-4 inhibitors have become one of the most frequently prescribed medications for type 2 diabetes in Japan, and we have previously reported the efficacy of a DPP-4 inhibitor, sitagliptin, in Japanese patients with type 2 diabetes." (PMID 23445717, 2013). "Thus, GLP-1 receptor agonists that are resistant to DPP-4 and DPP-4 inhibitors are currently being used for the treatment of type 2 diabetes." (PMID 24351817, 2013). "Dipeptidyl peptidase-4 (DPP-4) inhibitors are considered incretin enhancers, because they inhibit the enzymatic degradation of incretins, in particular, GLP-1 and therefore are established therapies for type 2 diabetes." (PMID 22125632, 2011). "In a cross-sectional study we studied the fasting serum DPP-4 enzymatic activity (sDPP-4) and the insulin resistance index (HOMA2-IR) in gliptin naïve patients with type 2 diabetes and in non-alcoholic fatty liver disease (NAFLD) and in healthy controls (CNTRL)." (PMID 20805868, 2010). "A study on type 2 diabetic patients using Twin Precision Nutrition observed significant improvements in metabolic health markers (e.g., Hba1C, weight, HOMA-IR), with most patients ceasing the use of medications (including insulin, metformin, DPP-4 inhibitors, and liraglutide)." (PMID 41305566, 2025). "While studies have examined immune cell changes after 3 months of using a DPP-4 inhibitor (sitagliptin) in type 2 diabetes patients, there is currently no research on the impact of a DPP-4 inhibitor on the immune system at 3 and 6 months in type 2 diabetes patients with chronic kidney disease." (PMID 38065905, 2023). "However, it remained uncertain whether DPP4 could reduce BDNF ratio (DBR) by targeting increased plasma DPP4 activity, thereby improving MCI in older patients with type 2 diabetes." (PMID 36909158, 2023). "Currently, people with type 2 diabetes are increasingly prescribed with newly introduced oral glucose‐lowering agents, such as sodium glucose co‐transporter 2 inhibitors (SGLT2 Is), glucagon‐like peptide‐1 receptor agonists (GLP‐1 RAs) or dipeptidyl peptidase‐4 inhibitors (DPP4 Is)." (PMID 36756713, 2023). "However, it important to note that DPP-4 inhibitors do not impair ex vivo T cell-dependent immune function in healthy individuals or patients with type 2 diabetes." (PMID 38065905, 2023). "The low risk of causing hypoglycaemia for metformin, DPP-4 inhibitors, GLP-1-Ras, and SGLT-2 inhibitors indicates that these antidiabetic drugs might be used for treatment of people with type 2 diabetes undertaking TRE regimens without major safety concerns." (PMID 35684097, 2022). "Therefore, we aimed to compare the clinical outcomes between dapagliflozin, empagliflozin, and dipeptidyl peptidase-4 inhibitors (DPP4i) in patients with type 2 diabetes without prior ASCVD, CKD, or HF." (PMID 36251654, 2022).
type 2 diabetes (continued). "Indeed, the increase in plasma DPP-4 levels observed in obese patients with type 2 diabetes compared to non-obese diabetic subjects was not accompanied by differences in DPP-4 activity." (PMID 35628332, 2022). "Similarly, dipeptidyl peptidase-4 inhibitors (DPP-4i) – a class of antihyperglycemic agents used for the treatment of Type 2 diabetes – have been reported as immunomodulators regardless of their glucose-lowering properties." (PMID 33906375, 2021). "Dipeptidyl peptidase-4 (DPP-4) inhibitors are a class of oral hypoglycemic agents that increase incretins such as glucagon-like peptide 1 (GLP-1) and glucose-dependent insulinotropic polypeptide, and they have been used widely in the treatment of type 2 diabetes." (PMID 31990936, 2020). "However, the DPP-4 inhibitor linagliptin increases the CX3CR1-positive monocytes with enhanced putative vasculoregenerative cells in type 2 diabetes patients with or without DN." (PMID 32365893, 2020). "Given the heterogeneity of patients with type 2 diabetes, it is likely that certain subgroups of patients may show better responses to SGLT2 inhibitors than to DPP‐4 inhibitors; such information may help clinicians determine which class of drug might be more suitable for specific patients." (PMID 31050099, 2019). "Incretins [dipeptidyl peptidase-4 inhibitors (DPP-4i) and glucagon-like peptide 1 RA (GLP-1 RA)] and sodium-glucose cotransporter-2 inhibitors (SGLT-2i) groups are now routinely used for type 2 diabetes therapy and comprise a large number of medicinal products." (PMID 31040779, 2019). "Furthermore, several studies demonstrated that DPP-4 inhibitors prevented increase in carotid intima-media thickness (IMT), an established marker of early-stage atherosclerosis, in patients with type 2 diabetes (T2DM) compared with conventional treatment." (PMID 29402270, 2018). "In the treatment of type 2 diabetes, there are largely used drugs that act, in part, by inhibiting the secretion or action of glucagon, such as glucagon-like peptide-1 (GLP-1) and GLP-1 receptor agonists, dipeptidyl peptidase-4 inhibitors (DPP-4), and metformin." (PMID 29670459, 2018). "However, because this distal site of action that cannot utilize tubuloglomerular feedback to ameliorate glomerular hyperfiltration, DPP-4 inhibition does not appear to exert early benefits on renal function in type 2 diabetes." (PMID 29310647, 2018). "However, some randomized clinical trials have reported that DPP-4 inhibitors failed to reduce cardiovascular events compared with placebo in patients with type 2 diabetes." (PMID 29017497, 2017). "In another study, however, DPP4 inhibitor sitagliptin as an add-on in type 2 diabetic patients for 6 months did not improve atherogenic lipids including total cholesterol, LDL cholesterol, and malondialdehyde-modified LDL (an oxidized LDL increased in diabetes)." (PMID 28619058, 2017). "For example, sitagliptin, a selective, potent dipeptidyl peptidase IV DPP-4 inhibitor, is the active ingredient in JANUVIA® and JANUMET® (a fixed dose combination with the antidiabetic agent metformin), which both recently received approval for the treatment of type 2 diabetes by the FDA." (PMID 28124975, 2017). "Moreover, a recent in vivo study showed that MK-0626, a DPP-4 inhibitor, had neutral effects on cortical and trabecular bone in an animal model of type 2 diabetes, and MK-0626 did not alter osteoblast differentiation." (PMID 27384445, 2016). "At the time of this review five DPP-4 inhibitors are approved by the European Medicines Agency (EMA) (vildagliptin, alogliptin, sitagliptin, linagliptin, and saxagliptin) for treatment of type 2 diabetes mellitus, also reflected by the Global Guideline for Type 2 Diabetes." (PMID 26251902, 2015).